LRP5 (LDL receptor related protein 5)
Diseases named in the same sentence as LRP5 in open-access papers (continued):
Sharing a sentence is not in itself a finding about the gene and the disease.
osteoporosis (continued). "Pathogenic variants in the LRP5, PLS3, or WNT1 genes can significantly affect bone mineral density, causing monogenic osteoporosis." (PMID 37277619, 2023). "Luteolin is a flavonoid found in many herbal extracts with antioxidant, anti-inflammatory and anti-tumor activities, and has been shown to reduce glucocorticoid-induced osteoporosis by modulating the ERK/Lrp-5/GSK-3β signaling pathway in vitro and in vivo." (PMID 36210811, 2022). "A similar 18-base-pair deletion eliminating six leucine residues within the LRP5 SP hydrophobic core was reported in a patient with Osteoporosis-Pseudoglioma Syndrome (OPPG)." (PMID 36362148, 2022). "Crispants involved with osteogenesis imperfecta (PLOD2) and osteoporosis (LRP5) were able to reproduce similar phenotypic characteristics, such as low BMD, like those of knockout mutants." (PMID 36225206, 2022). "Biallelic rare variants in LRP5 cause the autosomal recessive osteoporosis–pseudoglioma syndrome (OPPG, MIM 259770), characterized by generalized childhood-onset osteoporosis and blindness." (PMID 34236445, 2022). "Lrp5–/– mice have a normal morphological appearance and are viable and fertile, but exhibit osteoporosis, subtle defects in eye vasculature, and metabolic abnormalities, suggesting that LRP6 is more important than LRP5 in embryogenesis." (PMID 34026761, 2021). "The same approach was used to compare lrp5 crispants versus knockouts, showing similar results in both groups and validating the use of zebrafish crispants to study genes coupled to osteoporosis." (PMID 34938269, 2021). "Clinically, LRP5 functions essentially in bone mass and lipid metabolism in osteoporosis or cardiovascular patients." (PMID 34796178, 2021). "As a valuable therapeutic target in the treatment of osteoporosis and cardiometabolic disorders, the biological functions and molecular implications of Wnt-LRP5 regulations require further investigation." (PMID 34796178, 2021). "Loss of function mutations in the LRP5 gene result in osteoporosis-pseudoglioma syndrome (OPPG), a condition characterized by blindness and severe osteoporosis." (PMID 33101205, 2020). "Our study showed a strong association between osteoporosis and TT genotype of FDPS rs2297480, and with CC genotype of LRP5 rs3736228." (PMID 31774873, 2019). "Our study showed a strong association between bone mineral density and polymorphisms in the FDPS gene, and a borderline association with LRP5 and SOST polymorphisms in postmenopausal Romanian women with osteoporosis." (PMID 31774873, 2019). "For example, gain of functional variations in LRP5 gene leads to extremely high BMD and loss of functional variations in LRP5 gene results in osteoporosis-pseudoglioma syndrome." (PMID 30159320, 2018). "Polymorphisms of LRP5 have been demonstrated to have an influence on BMD and to be associated with an increased risk of osteoporosis." (PMID 27582019, 2016). "Further studies with larger sample sizes are needed to further clarify the role of LRP5 as a genetic determinant of osteoporosis." (PMID 27582019, 2016). "The polymorphisms of a number of genes, including vitamin D receptor, estrogen receptor α, estrogen receptor β, LRP5 and SOST, are associated with a risk of developing osteoporosis." (PMID 25815782, 2015). "We subjected LRP5 HBM knock-in mice to two different models of disuse osteoporosis—tail suspension and muscle paralysis." (PMID 26554834, 2015). "Variants in LRP5 and RUNX2 variants are also associated with bone mineral density and increased risk of osteoporosis, and osteoporotic fractures in association studies in Caucasians and Asian populations." (PMID 26719974, 2015). "To evaluate the bone-wasting effects of a second model of disuse osteoporosis—one involving reduced muscle stimulation due to paralysis—in Lrp5-HBM mice, we treated WT and HBM mice with unilateral hindlimb injection of Botox." (PMID 26554834, 2015).
osteoporosis (continued). "It has been demonstrated that the Wnt signaling pathway has an important role in the formation of bone and the pathogenesis of osteoporosis, and that LRP5 signaling is necessary for normal morphology, developmental processes, and bone health." (PMID 25580429, 2014). "Strong evidence for the essential role of canonical Wnt signaling is derived from the osteoporosis phenotype displayed in Wnt, LRP5 or β-catenin gene knockout mice." (PMID 24244491, 2013). "DKK1 overexpression is known for its pathological implications in osteoporosis, cancer, and neurodegeneration, suggesting the interaction with LRP5/6 as a potential therapeutic target." (PMID 27398238, 2012). "In vitro LRP5 studies by others have focused on HBM mutations and the few studies addressing the impact of mutations causing osteoporosis have mainly been associated with OPPG." (PMID 22487062, 2012). "Many bone disease-associated LRP5 polymorphisms have been extensively studied and can cause two opposite phenotypes: high bone mass (HBM) and osteoporosis." (PMID 21528003, 2011). "LRP5 polymorphisms associated with HBM are mostly missense mutations found in the first β-propeller domain, while those associated with osteoporosis often cause frame shift or nonsense mutations." (PMID 21528003, 2011). "Some weak associations with genetic markers within or near known osteoporosis candidate genes (i.e., ERα, CYP19, COLIA1, and LRP5) were detected." (PMID 20948561, 2010). "This work has established LRP5 as a major target for drug development to treat osteoporosis and other bone diseases." (PMID 20948575, 2010). "The discovery of linkage between the LRP5 gene and high bone mass was considered a genuine progress in the genetics of osteoporosis, a disorder that has been known to have a substantial genetic component." (PMID 18588671, 2008). "LRP5 knockout in mice decreased bone mass, as seen in osteoporosis." (PMID 40772209, 2025). "Conversely, LRP5 expression dysregulation contributes to pathological states such as osteoporosis–pseudoglioma syndrome, familial exudative vitreoretinopathy, high bone mass disorders, atherosclerosis, fibrotic renal and kidney diseases, and oncological diseases." (PMID 40940800, 2025). "Additionally, genes associated with rare monogenic forms of osteoporosis, such as SOST, CLCN7, and LRP5, have also been reported to influence BMD variation in diverse population studies." (PMID 41393297, 2025). "The patient inherited the PLS3 deletion from his unaffected mother and the LRP5 variant from his father with spinal osteoporosis but no fractures." (PMID 38043102, 2024). "Existen patologías asociadas a alteraciones en la señalización Wnt que desencadenan cuadros de osteoporosis precoz y riesgo de fractura, como las mutaciones con pérdida de función del LRP5 (síndrome de osteoporosis y seudoglioma) o mutaciónes de los Wnt." (PMID 38634083, 2024). "For example, the vitamin D receptor (VDR), collagen type I (COL1), estrogen receptor (ER), apolypoprotein Е (ApoE), bone morphogenetic protein (BMP), and Low-density lipoprotein receptor-related protein 5 (LRP5) are all involved in the pathogenesis of osteoporosis." (PMID 38098042, 2023). "The monoclonal antibody romosozumab has been used to prevent vertebral compression fractures in patients with osteoporosis, and functions by blocking the activity of the LRP5 inhibitor, sclerostin, leading to an increase in LRP5-mediated canonical WNT signaling." (PMID 37895195, 2023). "SOST and Dkk-1 can competitively bind to the co-receptor LRP5/6 in the Wnt signaling pathway and then regulate the transcription of downstream target genes, ultimately leading to the occurrence and development of osteoporosis." (PMID 36979418, 2023). "Since LRP5, PLS3, and WNT1 pathogenic variants cause osteoporosis, this was expected." (PMID 37277619, 2023).
osteoporosis (continued). "Furthermore, APS activated the expression of Wnt2, β-catenin, and LRP5 genes and inhibited oxidative stress in deovulated rats to reduce osteoporosis." (PMID 35877777, 2022). "Candidate osteoporosis genes commonly shared with AD and PD may include the LRP5 and LRP6 genes, which are partially affected by LRRK2 mutations, in the canonical Wnt signaling pathway." (PMID 34955816, 2021). "Similarly, when lrp5 was mutated in zebrafish it led to reduced BMD, bone volume and cortical thickness, reminiscent of osteoporosis." (PMID 34938269, 2021). "Patients harboring loss-of-function mutations in Wnt co-receptors LRP5 and LRP6 are more likely to suffer from impaired glucose homeostasis, coronary disease, and osteoporosis; in contrast, gain-of-function mutations in LRP5 are associated with increased adiposity and osteosclerosis." (PMID 32919095, 2020). "Our data reveled that Ps-GOS significantly up-regulates the expression of Wnt5a, LRP5, β-catenin, and Fzd4 mRNA, in MC3T3-E1 cells, suggesting that Ps-GOS may prevent bone loss in osteoporosis through Wnt/β-catenin together with BMP-2 signaling pathways." (PMID 32012654, 2020). "This study aimed to assess the relationship between bone mineral density and genotypes of four polymorphisms in previously detected osteoporosis-candidate genes (FDPS rs2297480, LRP5 rs3736228, SOST rs1234612, VKORC1 rs9934438) in postmenopausal Romanian women with primary osteoporosis." (PMID 31774873, 2019). "A potential interaction was reported between smoking and receptor-related Protein 5 (LRP5) C135242T (rs545382) on osteoporosis in postmenopausal women and between smoking and polymorphism of glutathione S-transferases (GSTT1) on bone quality index in young adult men." (PMID 30112011, 2018). "Specifically, we might develop drugs to activate and enhance the functions of LRP5 and β-catenin to treat osteoporosis." (PMID 28158288, 2017). "From our findings and limitations, it seems that LRP5 polymorphisms are not a risk factor for osteoporosis in Thai menopausal women." (PMID 27582019, 2016). "This study did not identify LRP5 polymorphisms as a risk factor for osteoporosis in Thai menopausal women." (PMID 27582019, 2016). "SNP in the LRP5 gene may considerably act as a potential candidate of biomarker for bone fracture and osteoporosis screening, diagnosis, and future treatment." (PMID 25580429, 2014). "Results identified that carriers of rs3736228 C>T variant in the LRP5 gene were associated with an increased risk of developing osteoporosis and fractures under 4 genetic models but not under the dominant model (OR = 1.19, 95% CI = 0.97~1.46, and P = 0.103)." (PMID 25580429, 2014). "This is not the first time that common variation within a gene that has previously been identified as underlying a rare monogenetic form of osteoporosis and/or high bone mass has been implicated in BMD regulation, other examples including the SOST, CLCN7 and LRP5 genes." (PMID 24176111, 2013). "However, primary osteoporosis and osteopenia have been confirmed in heterozygous carriers of OPPG-causing mutations located in other domains and on splice sites of LRP5." (PMID 22487062, 2012). "Information regarding the regulation of LRP5 gene expression may help us to understand its function and find potential new anabolic targets for conditions such as osteoporosis." (PMID 20141633, 2010). "Families previously diagnosed with Spondylo-ocular Syndrome with autosomal recessive inheritance, moderately severe-to-severe osteoporosis, and eye and hearing involvement without variants in LRP5, were discovered through WES to have mutations in Xylotransferase-2 (XYLT2)." (PMID 38942908, 2024). "Loss-of-function variants in LRP5 and WNT1 may lead to early-onset osteoporosis." (PMID 34236445, 2022).
osteoporosis (continued). "In mice, mutations in LRP5 were found to be associated with low BMD and abnormal retinal vasculature, while in humans, mutations in LRP5 were found to cause disorders characterized by high BMD and osteoporosis–pseudoglioma syndrome, causing severe osteoporosis and blindness." (PMID 33889153, 2021). "Indeed genetic polymorphisms of genes encoding androgen and estrogen receptors, IGF-I (insulin-like growth factor), vitamin D receptor and LRP-5 (low-density lipoprotein receptor-related protein 5) may be candidates affecting osteoporosis and sarcopenia." (PMID 32053970, 2020). "The LRP5 and β-catenin might be as therapeutic targets in osteoporosis treatment." (PMID 28158288, 2017). "However LRP5 contribution to osteoporosis in populations of other ethnicities remains poorly known." (PMID 24885293, 2014). "Therefore, it can be speculated that SNP rs3736228 C>T of the LRP5 gene could be regarded as a useful genetic biomarker for the prediction of osteoporosis and bone fracture." (PMID 25580429, 2014). "Loss-of-function mutations in human LRP5 gene cause the osteoporosis-pseudoglioma syndrome (OPPG), an autosomal-recessive condition of juvenile onset characterized by blindness due to aberrant vitreo-retinal vascular growth and osteoporosis resulting in fractures and deformation." (PMID 20141633, 2010). "The action of LRP5 on bone is mediated via DKK-1 antagonism of the Wnt pathway; hence, in osteoporosis, several antibodies targeting DKK-1 have been designed and tested in animal models, demonstrating excellent results." (PMID 40940800, 2025). "In one GWAS, key genes involved in osteoporosis were TNFRSF11B (OPG), TNFSF11 (RANKL), LRP5, and ESR1." (PMID 40772209, 2025). "European-focused GWAS have identified key loci for osteoporosis, including WNT signaling (SOST, LRP5) and RUNX2 transcriptional regulation." (PMID 40411668, 2025). "Given that the role of LRP5, PLS3, and WNT1 in the development of osteoporosis was only discovered 10–15 years ago, and the rarity of these pathogenic variants, their associated morbidity and prognosis are still largely undetermined." (PMID 37277619, 2023). "Therefore, LRP5 genetic variations may have an effect on osteoporosis within the Thai population." (PMID 27582019, 2016). "Therefore, therapeutic strategies, based on manipulation of LRP5 or canonical Wnt signaling, may be effective in targeting both osteoporosis and retinal vascular defects in OPPG patients, with the retinal vasculature being more resistant to potential side effects." (PMID 27031698, 2016). "While LRP6 is essential for embryogenesis, both LRP5 and LRP6 play critical roles for skeletal remodeling, osteoporosis pathogenesis and cancer formation, making LRP5 and LRP6 key therapeutic targets for cancer and disease treatment." (PMID 21887268, 2011). "Lrp5−/− mice and heterozygous Lrp6+/− mice are viable and exhibit OPPG/osteoporosis phenotypes demonstrating their overlapping functions in at least some aspects of bone development/homeostasis." (PMID 21887268, 2011). "Thus, common variants in LRP5 and LRP6 genes may contribute to normal population variance in human bone metabolism, and these two genes have been recently proposed and analyzed as putative osteoporosis candidate genes." (PMID 20948561, 2010). "A 2019 review summarized studies on low-density lipoprotein in metabolism, noting that during the study period, LRP5 was proven to play a role in osteosarcoma and in non-cancer conditions such as the chondrocytic subtype of prostate cancer and osteoporosis." (PMID 39445018, 2024). "Therefore, blocking the interaction between LRP5/6 and SOST is proposed as an effective treatment for osteoporosis." (PMID 36979418, 2023). "The LRP5 gene is involved in Wnt signaling (KEGG and Reactome databases) and also in several bone complications such as osteopetrosis, increased fracture rate, and osteoporosis with pseudoglioma (DisGeNET database)." (PMID 35742976, 2022).
osteoporosis (continued). "Recently, LRP5 has also been shown to play a role in chondroblastic subtype of osteosarcoma (OS) and prostate cancer and also in noncancer case such as osteoporosis." (PMID 31031810, 2019). "The purpose of the present study is to evaluate the relation between BMD and genotypes of four SNPs in previously reported osteoporosis candidate-genes (FDPS rs2297480, LRP5 rs3736228, SOST rs1234612, VKORC1 rs9934438) in a cohort of postmenopausal Romanian women." (PMID 31774873, 2019). "In the present study the role of LRP5 was explored further in 18 pediatric patients with primary osteoporosis without features of osteogenesis imperfecta (OI)." (PMID 22487062, 2012). "The phenols from areca nut seed was reported that it could relieve osteoporosis through regulating the expression of osteoprotegerin (OPG), RANKL, LDL-receptor relater protein 5 (LRP5), bone morphogenetic protein-2 (BMP2) and β-catenin related to the Wnt/β-catenin pathway in VOX-induced OP rats." (PMID 39449745, 2024). "LRP5 appears to be a major gene that could explain in part the low BMD and fractures in a selected population, which suggests that the failure of the Wnt pathway contributes to idiopathic osteoporosis." (PMID 30283887, 2018).